G0S2 (G0/G1 switch 2)
Description:
Promotes apoptosis by binding to BCL2, hence preventing the formation of protective BCL2-BAX heterodimers.
Tractability: PROTAC: its protein half-life has been measured.
Gene: Protein-coding gene on chromosome 1 (209,675,412 to 209,676,390, forward strand). Ensembl gene ENSG00000123689.
Subcellular location: Mitochondrion
Pathways (Reactome):
Metabolism: PPARA activates gene expression
Gene Ontology:
Molecular function: protein binding
Biological process: extrinsic apoptotic signaling pathway; positive regulation of extrinsic apoptotic signaling pathway; positive regulation of cold-induced thermogenesis
Cellular component: mitochondrion; lipid droplet
Genetic constraint (gnomAD): Loss-of-function variants: 0 observed, 0.36 expected, observed/expected ratio (o/e) 0, 90% interval 0 to 1.86. That is too few expected variants to judge how well the gene tolerates losing a copy. Missense variants: 139 observed, 125.76 expected, observed/expected ratio (o/e) 1.11, 90% interval 0.96 to 1.27. Synonymous variants: 64 observed, 56.51 expected, observed/expected ratio (o/e) 1.13, 90% interval 0.93 to 1.39.
Homologues: Orthologues: chimpanzee G0S2 (100% identical), macaque G0S2 (96% identical), mouse G0s2 (78% identical), rat G0s2 (77% identical), guinea pig G0S2 (69% identical), rabbit G0S2 (68% identical), pig G0S2 (67% identical), dog G0S2 (57% identical), tropical clawed frog G0S2 (49% identical), zebrafish g0s2 (26% identical).
Diseases named in the same sentence as G0S2 in open-access papers:
G0S2 is named in the same sentence as 77 diseases in open-access papers, as found by Europe PMC text mining. Sharing a sentence is not in itself a finding about the gene and the disease. The quoted sentences say what the papers report.
Obesity (14 papers, 2013 to 2026). Accumulation of substantial excess body fat. "Abcg1, Aldoa, Mrap, Pex13, Aldh6a1, Egln3, G0s2 and Syn2 are significantly increased in adipose or liver tissue of ob/ob mice compared with lean mice, suggesting these genes are associated with obesity, are very rarely reported to be related to adipogenesis." (PMID 34974794, 2022). "The highest G0S2 mRNA levels are observed in AT and, accordingly, G0S2-KO mice exhibit increased lipolysis, decreased AT mass, and resistance to diet-induced obesity when fed a high-fat diet." (PMID 32290093, 2020). "G0S2 KO in high fat diet-fed mice protects from obesity and insulin resistance, and increases thermogenesis." (PMID 27918443, 2016). "G0S2 knockout mice are lean, resistant to obesity by high fat feeding, glucose tolerant, insulin sensitive, and are more thermogenic." (PMID 26318046, 2015). "Further investigations are needed to address the functions of G0S2 in the pathophysiology of obesity-related hepatic steatosis in humans." (PMID 23951308, 2013). "Collectively, this study demonstrates that G0S2 may be a potential target gene for the treatment of obesity, NAFLD, and diabetes." (PMID 37033250, 2023). "First, because the small sample size is inadequate to generate conclusive data, it is necessary to conduct a large sample prospective cohort study in order to clarify the involvement of G0S2 in PBMC in the improvement of obesity-related impaired lipolysis by the treatment with ALA." (PMID 26912161, 2016). "The mechanism of NET in the prevention and treatment of obesity needs to be further studied, knowing that regulation of G0S2 and ATGL may prove to be a new strategy for the treatment of obesity." (PMID 24641917, 2014). "Excessive G0S2 inhibits lipolysis in vivo during active lipolytic conditions, such as food restriction and fasting, suggesting G0S2 as a potential target for treatment of obesity." (PMID 24964090, 2014). "This suggests that G0S2 is a key regulator of energy homeostasis, mediating lipolysis and fatty acid oxidation, and a downregulation of this gene could be beneficial in the treatment of both obesity and obesity-related diseases." (PMID 27918443, 2016). "Taken together, our results provide evidence supporting an important role for G0S2 as a regulator of triglyceride content in the liver and suggest that G0S2 may be a molecular target for the treatment of insulin resistance and other obesity-related metabolic disorders." (PMID 23951308, 2013). "Among them, the upregulated gene BCL2A1 is common in CVD, HTN, obesity, and aging; RNF144B and PTGIS are common in HCL, obesity, aging, and CVD; G0S2, CXCL1, ACKR3, and PTPRD are found in HTN, aging, and CVD; TGFB2, CA12, and MSR1 are familiar in obesity, aging, and CVD." (PMID 36035865, 2022). "This study shows that overexpression of the G0S2 gene aggravates liver insulin resistance of mice through upregulating P-Foxo1, Socs3, and Ptpn1 and downregulating Gstp1 and Ppar-γ, which demonstrates that G0S2 may be a potential target gene for the treatment of NAFLD, obesity, and diabetes." (PMID 37033250, 2023).
breast carcinoma (7 papers, 2021 to 2026). "High expression levels of the protein G0/G1 Switch 2 (G0S2) which regulates lipid metabolism via peroxisome proliferator-activated receptor-α (PPARα) were recently reported to associate with a decrease in breast cancer recurrence rates." (PMID 35911770, 2022). "Yim has reported that low G0S2 expression in breast cancer, particularly estrogen receptor-positive breast cancer, correlates with increased rates of its recurrence." (PMID 36366842, 2023). "The sensitivity of G0/G1 transition gene 2 (G0S2) breast cancer cells to tamoxifen was relatively increased, which makes G0S2 an antitumor breast cancer target and biomarker of recurrence and therapeutic response." (PMID 34367284, 2021). "G0S2 has been shown to promote anti-estrogenic and pro-migratory responses in breast cancer cells." (PMID 40519301, 2025). "In tumor cells, especially in cancer cell lines like breast cancer cells and lipoma cells where G0S2 expression is significantly upregulated compared to normal cells, it is not elucidated whether G0S2 also has a promoting effect on F0F1-ATP synthase." (PMID 35912266, 2022).
Hepatic steatosis (6 papers, 2013 to 2025). Steatosis is a term used to denote lipid accumulation within hepatocytes. "G0S2 plays an important role in inducing hepatic steatosis through downregulation of UPR signaling, while regulating lipolysis and energy metabolism by inhibiting adipose triglyceride lipase (ATGL)." (PMID 37033250, 2023). "G0S2 can modulate the lipolysis process by interacting with ATGL, and the level of G0S2 is upregulated in the occurrence of fatty liver disease in mice." (PMID 37033250, 2023). "Specifically, recent studies showed that G0S2 is critical for triglyceride accumulation in the liver and is an important contributor to the development of liver steatosis." (PMID 33449950, 2021). "On the other hand, recent studies have reported that targeted disruption of G0S2 alters hepatic energy balance and overexpression of this gene induces triglyceride accumulation in the mouse liver leading to development of hepatic steatosis." (PMID 26482123, 2015). "Interfering with AT-lipolysis or hepatic G0S2 expression represents an effective strategy for the treatment of hepatic steatosis." (PMID 25733154, 2015). "In the present study, we found that the overexpression of G0S2 induces triglyceride accumulation in the mouse liver and results in the development of hepatic steatosis." (PMID 23951308, 2013). "In the present study, we provided direct evidence that G0S2 induced liver triglyceride accumulation and severe hepatic steatosis under basal conditions." (PMID 23951308, 2013). "It is worth noting that G0S2-induced hepatic steatosis was very potent (by 3-fold) in vivo, but to a lesser extent (1.5-fold) in hepatocytes in vitro." (PMID 23951308, 2013). "In fact, a significant reduction in hepatic steatosis was observed in mice receiving G0s2–/– WAT." (PMID 40100923, 2025). "In line with this conclusion, liver-specific G0S2 overexpression leads to hepatic steatosis." (PMID 25733154, 2015). "Under conditions of increased plasma FA levels, as exemplified in mice fed a HFD, a sustained G0S2-mediated suppression of hepatic TG catabolism may lead to the development of hepatic steatosis and the activation of the UPR." (PMID 25733154, 2015). "The differences between the in vitro and in vivo results may indicate that internal conditions can modulate G0S2 activity and the global metabolic effects of G0S2 may also contribute to the development of hepatic steatosis." (PMID 23951308, 2013). "Adenovirus-mediated expression of G0S2 (Ad-G0S2) potently induced fatty liver in mice." (PMID 23951308, 2013). "G0S2 knockout mice exhibit a lower level of hepatic triglycerides and were resistant to HFD-induced liver steatosis." (PMID 37033250, 2023).
Insulin resistance (5 papers, 2013 to 2025). Increased resistance towards insulin, that is, diminished effectiveness of insulin in reducing blood glucose levels. "The upregulation of G0S2, may be beneficial in preventing excessive lipolysis and the consequent release of free fatty acids into circulation, which is associated with insulin resistance and metabolic dysfunction." (PMID 40909882, 2025). "However, the mechanisms underlying the relationship between G0S2 and insulin resistance remain incompletely understood." (PMID 37033250, 2023). "Thus far, the precise underlying mechanisms of G0S2 in the regulation of insulin resistance-related NAFLD are still unknown." (PMID 37033250, 2023). "Our research demonstrates that the expression patterns of several proteins associated with insulin signaling pathway are consistent with the change of insulin resistance after overexpression of G0S2." (PMID 37033250, 2023). "G0s2, a G0/G1 switch gene 2, shows an inhibitory capacity for the lipolytic enzyme adipose triglyceride lipase (ATGL), and the deletion of G0s2 ameliorates high-fat diet induced body weight gain and insulin resistance." (PMID 31337008, 2019). "Our study aimed to confirm the effect of G0S2 on insulin resistance, and determine whether the insulin resistance in mice fed a high-fat diet (HFD) results from G0S2 elevation." (PMID 37033250, 2023). "In conclusion, we focused our study on the effect of G0S2 on insulin resistance." (PMID 37033250, 2023). "However, the mechanisms of G0S2 in insulin resistance-related NAFLD are still unknown." (PMID 37033250, 2023). "Deletion of the G0S2 gene alleviates HFD-induced NAFLD and insulin resistance." (PMID 37033250, 2023). "Insulin resistance is likely an important determinant of the negative effects of G0S2 targeting NAFLD and diabetes." (PMID 37033250, 2023). "Another limitation is that we did not test the effects of G0S2 gene deletion to determine whether such deletion is sufficient to improve insulin resistance." (PMID 37033250, 2023).
Sepsis (5 papers, 2020 to 2025). Sepsis is defined as life-threatening organ dysfunction caused by a dysregulated host response to infection. "The identified FAM89A, FFAR3, G0S2, and FGF13 genes may help elucidate the molecular mechanisms underlying sepsis and drive the introduction of new biomarkers to advance diagnosis and treatment." (PMID 38050254, 2023). "Therefore, it appears likely that FFAR3, G0S2, and FGF13 participate in inflammation and metabolic reprogramming during sepsis." (PMID 38050254, 2023). "Although there are no direct evidences on the relationship between G0S2, PRUNE2, SLC22A4 and septic shock or sepsis, several researches indicated their indirect association." (PMID 34772470, 2021).
glioblastoma (4 papers, 2018 to 2025). The most malignant astrocytic tumor (WHO grade IV). "Through comprehensive analysis of TCGA and CGGA datasets, we revealed that BCL2 as a G0S2-suppressed target gene that demonstrates low expression in glioblastoma (GBM)." (PMID 40519301, 2025). "G0S2 was identified as a prospective biomarker in glioblastoma stem-like cells, and the methylation-induced downregulation of G0S2 was linked to the inhibited invasion of IDH1-mutant glioblastoma cells and an improved prognosis." (PMID 38672263, 2024). "Additionally, we revealed that the overexpression of the DNA demethylase Ten-eleven translocation 2 (TET2) in IDH1-plasmid transfected glioblastoma multiforme (GBM) cells restored G0S2 expression." (PMID 30388142, 2018).
coronary atherosclerosis (3 papers, 2020 to 2024). Atherosclerosis of the coronary vasculature. "A retrospective clinical study on coronary atherosclerosis demonstrated that G0S2 expression in peripheral blood leukocytes is an independent risk factor for AMI in patients with stable CAD." (PMID 38867262, 2024). "We demonstrated that in myocardium coronary atherosclerosis increases only the transcript level of G0S2 and FABP4." (PMID 31979197, 2020). "Previously, only one study has reported the role of G0S2 in coronary artery atherosclerosis." (PMID 35769488, 2022). "On the opposite, coronary atherosclerosis substantially elevated the mRNA level of G0S2 (+102.3%, p < 0.05), however, it did not change its protein content." (PMID 31979197, 2020). "Therefore, we examined both myocardial and perivascular adipose tissue expression of ATGL, CGI-58, G0S2, HSL, and FABP4 at the transcript (mRNA) and protein levels in patients with multivessel coronary artery disease and compared them with control patients without coronary atherosclerosis." (PMID 31979197, 2020).
glioma (3 papers, 2018 to 2025). A benign or malignant brain and spinal cord tumor that arises from glial cells (astrocytes, oligodendrocytes, ependymal cells). "In this study, we elucidated the role of G0S2 in glioma cell invasion and identified a mechanism by which patients with glioma carrying IDH mutations and G-CIMP show better prognosis." (PMID 30388142, 2018). "In this study, we revealed the functional role of G0S2 in glioma and elucidated one explanation for the increased survival in glioma with IDH1 mutation." (PMID 30388142, 2018). "In contrast, overexpression of G0S2 increased the resistance of glioma cell and tumor to IR treatments, demonstrating an undescribed function of G0S2 in glioma radioresistance." (PMID 30953555, 2019). "In this study, we demonstrate that G0S2-induced radioresistance is related with G0S2-regulated lipid droplet stability in gliomas." (PMID 30953555, 2019). "We then assessed the role of G0S2 in radiation response in glioma stem-like cells (GSCs) and glioma cell lines." (PMID 30953555, 2019). "In sum, these results show that 53BP1 protein expression is regulated by G0S2 in glioma cell responses to IR treatment." (PMID 30953555, 2019). "The newly elucidated roles of G0S2 in glioma radioresistance also provide a strong rationale for targeting this molecule in clinical treatment of human gliomas." (PMID 30953555, 2019). "To further demonstrate that G0S2 regulates glioma radioresistance through 53BP1, we knocked down 53BP1 using shRNAs in U87/G0S2 and LN229/G0S2 cells and determined γ-H2AX expression and γ-H2AX foci formation in response to IR." (PMID 30953555, 2019). "Modulation of G0S2 expression affects GBM responses to IR treatments in vitro and in vivo through mTOR/S6K/RNF168/53BP1-regulated DNA repair, suggesting G0S2 as a potential mediator of glioma responses to IR." (PMID 30953555, 2019). "Taken together, these data support that G0S2 regulates glioma radioresistance through mediating 53BP1 stability in response to IR." (PMID 30953555, 2019). "Here, our results support this notion and show that G0S2 overexpression inhibited 53BP1 ubiquitination and upregulated 53BP1 foci cell formation in glioma cells, and thereby reduced γ-H2AX expression and γ-H2AX foci cell formation in response to irradiation." (PMID 30953555, 2019). "Here, by analyzing gene expression profiles in glioma stem cells (GSCs) treated with fractionated radiation, we found that G0S2 is significantly upregulated in radioresistant GSCs." (PMID 30953555, 2019). "Since 53BP1 stability is regulated by ubiquitination in DNA repair, we tested if G0S2 regulates 53BP1 ubiquitination and stability in glioma cells in response to IR." (PMID 30953555, 2019). "Our results demonstrate that G0S2 regulates glioma radioresistance through mTOR/S6K/ RNF168/53BP1-regulated DNA repair." (PMID 30953555, 2019). "Our data demonstrate for the first time that G0S2 functions as a mediator of radiation resistance in gliomas." (PMID 30953555, 2019). "By using genetic approaches targeting G0S2, we found that shRNA knockdown of G0S2 inhibited glioma tumorigenesis in vivo." (PMID 30953555, 2019). "Knockdown of G0S2 by shRNAs sensitized glioma cells to IR treatments in vitro and glioma tumorigenicity." (PMID 30953555, 2019). "Last, we examined the relationship of G0S2 expression and glioma patient survival by Kaplan–Meier survival analysis using the GSE13041 dataset." (PMID 30953555, 2019). "Using genetic approaches targeting G0S2 in glioma cells and GSCs, we found that knockdown of G0S2 promoted lipid droplet turnover, inhibited GSC radioresistance, and extended survival of xenograft tumor mice with or without IR." (PMID 30953555, 2019). "To verify the role of G0S2 in glioma malignancy, we measured G0S2 gene expression in WHO grade II diffuse astrocytoma, grade III anaplastic astrocytoma, and grade IV primary GBM tissue samples." (PMID 30388142, 2018).